EPHA4 (EPH receptor A4)
Diseases named in the same sentence as EPHA4 in open-access papers (continued):
Sharing a sentence is not in itself a finding about the gene and the disease.
gastric cancer (9 papers, 2013 to 2025). A primary or metastatic malignant neoplasm involving the stomach. "Overexpression of EPHA4 is associated with poor prognosis in patients with gastric cancer." (PMID 35204461, 2022). "It has been previously reported that high expression of EphA4 is correlated with the prognosis of patients with breast and gastric cancers." (PMID 26516928, 2015). "In gastric cancer EPHA4 overexpression has been correlated with poor prognosis and depletion of EPHA via siRNA resulted in decreased proliferation and lower migration." (PMID 26376612, 2015). "We therefore examined the relation between clinical outcomes and immunohistochemical expression of EphA2, EphA4, and ephrinA1 in gastric cancer." (PMID 23738943, 2013). "EphA4 plays an important role in tumour progression and clinical outcomes, similar to EphA2, in patients with gastric cancer." (PMID 23738943, 2013). "Our findings are consistent with those of a previous study showing that overexpression of EphA4 on immunohistochemical analysis is an independent predictor of overall survival in gastric cancer." (PMID 23738943, 2013). "EphA4 was an independent prognostic factor in gastric cancer, even in advanced disease requiring adjuvant chemotherapy after resection to prevent recurrence." (PMID 23738943, 2013). "The EPHA4 mutation has also been reported in cutaneous melanomas and characterized as a negative prognostic factor for gastric cancer patients, whereas it is associated with better OS in lung cancer patients." (PMID 41516312, 2025). "For example, EphA1 and EphA4 are upregulated in gastric cancer; EphA2 overexpression in mammary epithelial cells induces tumorigenesis and EphA8 stimulates the proliferation, invasion, and migration of gastric cancer cells." (PMID 35681118, 2022). "In addition to Sézary syndrome, EPHA4 has also been found to be overexpressed in several different types of solid tumors, such as prostate, pancreatic, liver and gastric cancer." (PMID 26376612, 2015). "Our results suggest that high expression of EphA4 and EphA2 may play critical roles in tumor progression, metastasis, and outcomes in gastric cancer." (PMID 23738943, 2013). "High gene expression of EphA4 has been linked to overexpression of the protein in gastric cancer, whereas EphA4 gene amplification has not." (PMID 23738943, 2013). "EphA4 may be a promising target for monoclonal antibody therapy in patients with gastric cancer." (PMID 23738943, 2013). "EphA4 may play important roles in tumor progression and outcomes in patients with gastric cancer." (PMID 23738943, 2013). "EphA4 is an independent prognostic factor in stage II and III gastric cancer, stages that usually require adjuvant chemotherapy." (PMID 23738943, 2013). "While this gene has not been directly linked to Hippo, the related EphA2 receptor was shown to regulate YAP in breast and gastric cancer cells and other EPHA receptors (EPHA4, EPHA5, EPHA7 and EPHA8) emerged as Hippo pathway activators in an siRNA screen in HEK293T cells." (PMID 40869130, 2025). "Gene expression or quantitative assessment is important and necessary to confirm the outcomes of this study, although mRNA expression levels of EphA2, EphA4, and ephrinA1 were shown to be higher in gastric cancer tissue than in non-cancerous gastric tissue by other investigators." (PMID 23738943, 2013).
glioma (9 papers, 2014 to 2024). A benign or malignant brain and spinal cord tumor that arises from glial cells (astrocytes, oligodendrocytes, ependymal cells). "High expression of the ephrin type-A receptor 4 (EPHA4) gene in glioma cells was found to potentiate FGF2–FGFR1 signaling and promote cell growth and migration through the AKT/MAPK and RAC1/CDC42 pathways, respectively." (PMID 38255923, 2024). "For instance, EphA4 promotes cell proliferation and migration of glioma cells through the FGFR1 signalling pathway." (PMID 33741023, 2021). "In the subnetworks, several kinases, such as ABL1, ACVR1, EPHA4, MAPK9, PAK1 and SRC, were commonly associated with glioma, cell migration and cell death/survival." (PMID 32392905, 2020). "In this study, a high expression of EPHA4 in glioma cells was found to potentiate FGF2–FGFR1 signaling and promoted cell growth and migration through the AKT/MAPK and RAC1/CDC42 pathways, respectively." (PMID 31337028, 2019). "Upregulation of EPHA4, a receptor tyrosine kinase which binds ephrin family ligands, modulates cell morphology and promotes migration in glioma cells." (PMID 28341962, 2017). "FGFRs directly interact with EphA4 to promote cell proliferation in tumors such as glioma." (PMID 35096972, 2021). "Six out of the 17 interactions have been previously linked to invasion, migration or adhesion (EPHA4-Efnb3, SEMA5A-Plxnb3, AQP4-Dag1, FGFR1-Ncam1, FGF2-Sdc2, and APP-Aplp2) whereas only 3 interactions have been previously reported in glioma (SEMA5A-Plxnb3, AQP4-Dag1, and FGF2-Sdc2)." (PMID 25365423, 2014). "Cell contact-mediated bidirectional EFNB3/EPHA4 signaling and migration of interneurons during cerebral cortex development has been previously reported, suggesting the possible usage of this interaction during glioma invasion." (PMID 25365423, 2014). "In addition, a potential cell-cell interaction between Efnb3 expressing cells at the microenvironment and EPHA4 expressing glioma cells at the AOI was suggested." (PMID 25365423, 2014). "EPHA4 transactivated FGFR1 in the U251 glioma cell line, promoting cell growth and migration, and EPHA4 expression is increased in glioma." (PMID 31337028, 2019).
cervical carcinoma (8 papers, 2008 to 2023). A carcinoma arising from either the exocervical squamous epithelium or the endocervical glandular epithelium. "The down-regulation of EPHA4 was previously reported in cervical cancer." (PMID 30020984, 2018). "Additionally, IGF1R, N-myc and EphA4 were generally expressed at a high level in 14 pairs of clinical cervical carcinoma tissue samples." (PMID 27487126, 2017). "RSU1P2, a pseudogene of Ras suppressor protein 1, is upregulated in cervical cancer and promotes tumorigenic phenotypes by sponging let-7a from IGF1R (insulin like growth factor 1 receptor), MYCN, and EPHA4 (EPH receptor A4)." (PMID 29702599, 2018). "For example, the lncRNA Ras suppressor protein 1 pseudogene 2 (RSU1P2) was shown to be overexpressed in cervical cancer and to play a tumor-promoting role by acting as a ceRNA for microRNA let-7a and regulating the expression of IGF1R, N-myc, and EphA4." (PMID 28209205, 2017). "Furthermore, we revealed that the binding of RSU1P2 to the let-7a miRNA relieved the suppression of the let-7a-targeted genes IGF1R, N-myc and EphA4, which may explain role of RSU1P2 in tumorigenesis of cervical cancer." (PMID 27487126, 2017).
prostate carcinoma (8 papers, 2013 to 2024). A carcinoma that arises from epithelial cells of the prostate gland. "The linkage of EphA4 with prostate cancer associated receptor ERBB3/HER3 is apparent from the observed decrease of EphA4 transcript following the knockdown of ERBB3 in DU145 cells." (PMID 29682554, 2018). "Comparable trends are apparent for EphA4; its importance has been highlighted through siRNA knockdown, which resulted in a reduction in prostate cancer cell viability." (PMID 33430066, 2021). "An increase in EphA4 mRNA and protein levels has been reported when prostatic intraepithelial neoplasia progresses to prostate carcinoma, and knockdown of EphA4 has shown altered viability and colony forming ability of cancer cells." (PMID 29682554, 2018). "EphA4 has also been found to be expressed at higher levels in prostate cancer cells compared to normal prostate epithelium and has been suggested to play a tumour promoting role in prostate cancer progression." (PMID 24795148, 2014). "Activated EphA4 and EphA2 have been shown to trigger the activation of RhoA, which ultimately led to reinitiation of migration in a different direction in a prostate cancer cell line." (PMID 23738943, 2013). "Here we show that CIL between prostate cancer cells is regulated by EphA receptors, specifically EphA2 and EphA4." (PMID 23495724, 2013). "EphA4 expression is also related to a more aggressive phenotype, and its significance has been emphasised by siRNA silencing, which led to a decrease in the viability of prostate cancer cells." (PMID 36830852, 2023).
Stroke (8 papers, 2017 to 2026). Sudden impairment of blood flow to a part of the brain due to occlusion or rupture of an artery to the brain. "Because reactive astrocytes and post-stroke plasticity are closely linked, the contribution of environmental enrichment and EphA4 inhibition on astrocytic phenotypes, glial scar formation and axonal plasticity would be an interesting mechanism to assess." (PMID 31814004, 2020). "To implement rehabilitation in our functional EphA4 targeted experiment, we first assessed the effectiveness of a basic enriched environment on functional outcome after experimental stroke." (PMID 31814004, 2020). "Although EphA4 levels increase after experimental stroke, subacute EphA4 inhibition followed by environmental enrichment does not further increase recovery." (PMID 31814004, 2020). "EphA4 protein levels increased in the ipsi- and contralesional cortex and returned to baseline levels at 4 weeks after stroke." (PMID 31814004, 2020). "To study the role of EphA4 targeted therapy in stroke recovery, we first examined EphA4 cell-type specific expression within the motor cortex using an EphA4 reporter mouse (EphA4LacZ)." (PMID 31814004, 2020). "After experimental stroke, reduced EphA4 levels improve functional outcome with similar beneficial effects upon the inhibition of EphA4 downstream targets." (PMID 31814004, 2020). "The majority of surviving neurons in the ipsilesional cortex expressed Epha4 during the subacute and chronic phase after stroke." (PMID 31814004, 2020). "In this study, we assessed the effectiveness of a basic enriched environment in the chronic phase after photothrombotic stroke in mice as well as the therapeutic potential of EphA4 targeted therapy followed by rehabilitation." (PMID 31814004, 2020). "In this study, we assessed the effect of subacute EphA4 targeted therapy in combination with environmental enrichment during the chronic phase after photothrombotic stroke." (PMID 31814004, 2020). "We assessed both the efficacy of the enriched environment as well as the possible therapeutic relevance of EphA4 inhibition in combination with environmental enrichment to improve stroke recovery." (PMID 31814004, 2020). "Previously, we showed that constitutive EphA4 knockdown improves stroke outcome, and blocking EphA4 downstream signaling results in a similar beneficial effect." (PMID 31814004, 2020). "After experimental stroke, EphA4 phosphorylation levels at one of its tyrosine residues (Tyr602) remained stable during the acute (24 h), subacute (day 7) and chronic phase (day 21)." (PMID 31814004, 2020). "Other groups have documented astrocytic Epha4 gene expression after experimental stroke and other CNS injury models." (PMID 31814004, 2020). "In C57BL/6J mice, RNAscope in situ hybridization with probes specific for neurons (Syp), astrocytes (Slc1a3) and EphA4 (Epha4) showed that at 1 week post-stroke, Epha4 was expressed in 61% of Syp + neurons and 15% of Slc1a3+ astrocytes." (PMID 31814004, 2020). "Double immunostainings with antibodies against β-gal and neuronal (NeuN), astrocytic (GFAP) or microglial (CD11b) markers identified the presence of the EphA4/β-gal fusion protein in neurons at 2 weeks and 3 weeks after experimental stroke in EphA4LacZ mice." (PMID 31814004, 2020). "EphA4 expression is up-regulated in axonal stumps after injury and in sprouting neurons of aged mice after stroke, which contributes to reduced recovery." (PMID 28526745, 2017). "EphA4 is up-regulated in spinal cord injury, traumatic brain injury, and stroke, and blocking of the receptor increases functional recovery in models for these conditions (7, –, 9)." (PMID 28526745, 2017). "Moreover, during development EphA4 is expressed by MNs undergoing programed cell death, while blockade of EphA4 signaling can limit cell death in models of stroke." (PMID 38224498, 2024).
Stroke (continued). "EphA4 might be an important regulator of stroke recovery since aged animals increase Epha4 expression in post-stroke sprouting neurons compared to young animals." (PMID 31814004, 2020). "In the present study, we first identified Epha4 expression patterns after photothrombotic stroke." (PMID 31814004, 2020). "Thus, it is possible that higher levels of EphA4 inhibition are needed in order to achieve benefits on stroke outcome." (PMID 31814004, 2020). "Furthermore, EphA4 is upregulated in post-stroke sprouting neurons in aged compared to younger rats, possibly contributing to reduced recovery potential in aged animals." (PMID 31814004, 2020). "Although total EphA2/3/4/5 phosphorylation increases during the first week after middle cerebral artery occlusion (MCAO), EphA4 phosphorylation relative to total EphA4 protein levels remained unaltered during the acute, subacute and chronic phase after photothrombotic stroke." (PMID 31814004, 2020). "To evaluate potential differences in EphA4 and ephrin levels after changing environmental conditions, we determined EphA4 and ephrin ligand expression in the ipsi- and contralesional cortex at 5 weeks after experimental stroke." (PMID 31814004, 2020). "Although astrocytic EphA4 influences glial scar formation and axonal outgrowth after spinal cord injury, we detected only limited Epha4 expression in ipsilesional astrocytes at day 7 post-stroke." (PMID 31814004, 2020). "Furthermore, we did not assess the effect of the enriched environment and/or EphA4 targeted therapy on mechanisms underlying stroke recovery, including axonal plasticity and glial scar formation." (PMID 31814004, 2020). "In addition, we showed that EphA4 reduction improves functional outcome after experimental stroke." (PMID 31814004, 2020). "Additionally, EphA4 protein levels were increased from 24 h to 21 days after stroke." (PMID 31814004, 2020). "Indeed, total cortical Epha4 mRNA levels at the same time point post-stroke (day 7) were elevated." (PMID 31814004, 2020). "In order to assess the translational potential of rehabilitation with EphA4 targeted therapy, we implanted micro-osmotic pumps and ipsilesional ICV infusion cannulas during the same surgical procedure as the induction of stroke in C57BL/6J mice." (PMID 31814004, 2020). "Comparing stroke and non-stroke conditions, no changes in Epha4 puncta/μm2 in neurons nor astrocytes were detected." (PMID 31814004, 2020). "Although we did not detect post-stroke differences in Epha4 puncta/μm2 in neurons nor astrocytes using in situ hybridization, total Epha4 mRNA levels in cortical tissue were elevated at day 7 post-stroke." (PMID 31814004, 2020). "The percentage of Epha4+ neurons and Epha4+ astrocytes did not change compared to baseline non-stroke conditions (63 and 10%, respectively)." (PMID 31814004, 2020). "In conclusion, we show that environmental enrichment during the chronic phase of stroke improves functional outcome in mice with no synergistic effects of the used EphA4 targeted therapy." (PMID 31814004, 2020). "In the present study, we show that rehabilitation during the chronic phase after photothrombotic stroke persistently improves functional outcome at least up to 2 months after injury without synergistic effects of EphA4 inhibition." (PMID 31814004, 2020). "EphA4 inhibition by APY-d3 peptide treatment for 2 weeks starting at day 2 after experimental stroke did not result in beneficial effects on stroke recovery." (PMID 31814004, 2020). "Overall, our findings indicate that an enriched environment improves functional outcome even when initiated in the chronic phase after experimental stroke and that the subacute EphA4 targeted therapy we employed does not have additional beneficial effects." (PMID 31814004, 2020).
Stroke (continued). "Epha4 expression levels analyzed by the number of Epha4 puncta/μm2 in neurons or astrocytes did not significantly change although a trend towards increased numbers of puncta in the stroke versus non-stroke condition was present for both cell types." (PMID 31814004, 2020). "Exposure to an enriched environment resulted in a persistent functional improvement until the final follow-up at day 63 after stroke, without synergistic effects of EphA4 targeted therapy." (PMID 31814004, 2020). "Moreover, prior studies have suggested that EphA4, another RTK, negatively regulates post‐stroke collateral changes and may act as an upstream modulator of Tie2." (PMID 41164967, 2026).
glioblastoma (7 papers, 2008 to 2023). The most malignant astrocytic tumor (WHO grade IV). "The results revealed that EphA2, EphB2, EphB3, and EphB4 were significantly upregulated, while EphA4 and EphB6 were significantly downregulated in glioblastoma than normal brain tissues, respectively." (PMID 37146061, 2023). "The pair EphA4/Ephrin-B3 favors survival of neuronal progenitors of the brain subventricular zone, an area where glioblastoma multiform (GBM) are thought to originate." (PMID 28423606, 2017). "Ephrin-B3 via its ability to block EphA4-induced apoptosis is likely involved in glioblastoma tumorigenesis, since its specific invalidation is sufficient to slow down tumor growth in a xenograft model." (PMID 28423606, 2017). "Co-silencing of EphA4 resulted in the rescue of the angiogenic defects, suggesting that enhancing EphA4-induced cell death could be envisaged as a relevant strategy to slow glioblastoma (GBM) growth." (PMID 35565373, 2022).
colon carcinoma (6 papers, 2019 to 2023). "Also, analysis of paired normal colon tissue and colon cancer (n = 26) showed that mRNA levels of EphB2, EphB3, EphB4, and EphA4 are significantly lower in the normal tissue than in the adjacent cancer, whereas levels of EphrinB2 and EphB1 are similar." (PMID 31545551, 2019). "While EPHA4 signaling promotes mesenchymal-to-epithelial transition during morphogenesis in zebra fish embryo development, it was reported that overexpression of EPHB3 enhances cell–cell contacts and inhibits the growth in HT-29 human colon cancer cells." (PMID 37239828, 2023).